ICOS (inducible T cell costimulator)
Diseases named in the same sentence as ICOS in open-access papers (continued):
Sharing a sentence is not in itself a finding about the gene and the disease.
infection (continued). "Although the significant differences of Th1 and Treg cells in spleen and/or lymph nodes between ICOS KO mice and their WT controls were observed before infection, both Th1 and Treg cells, which were reported to downregulate hepatic granuloma formation, were less in infected ICOSL KO mice livers." (PMID 24788758, 2014). "Thus, in contrast to IL-4-secreting CXCR5+ Tfh cells, not only are Th2 effector cell responses efficiently generated in ICOS−/− mice, it appears that ICOS is in fact involved in suppressing Th2 cell effector responses at the infection site." (PMID 23319295, 2013). "Thus, upon infection, H. polygyrus preferentially expands Helios−Foxp3+ adaptive Treg cells within the LP in an ICOS-dependent manner." (PMID 23319295, 2013). "In summary, this study demonstrates that ICOS plays key roles in eliciting Foxp3+ Treg-cell responses during infections with the nematode H. polygyrus and the trematode S. mansoni, both locally at the infection site and systemically within the LN and spleen." (PMID 23319295, 2013). "Impaired lamina propria Foxp3+ Treg-cell responses were associated with increased production of IL-4 and IL-13 by CD4+ T cells, demonstrating that ICOS dominantly downregulates Type 2 responses at the infection site, sharply contrasting with its Type 2-promoting effects within lymphoid tissue." (PMID 23319295, 2013). "Infection with H. polygyrus did not change the percentage of MLN CD4+Foxp3+ Treg cells in either WT or ICOS−/− mice, indicating that ICOS deficiency impaired the expansion of CD4+Foxp3+ Treg cells and CD4+Foxp3− Teff cells to a similar extent." (PMID 23319295, 2013). "Thus, in contrast to the MLN, ICOS deficiency resulted in an elevated production of Type 2 cytokines by CD4+ T cells within the LP, suggesting that ICOS downregulates Th2 cells at the infection site." (PMID 23319295, 2013). "Furthermore, ICOS-KO mice continued to lose weight beyond day 10 post-infection, whereas WT mice started to recover." (PMID 23285133, 2012). "However, at the later phase of infection (around day 10 post-infection), ICOS-YF mice started to recover body weight similar to WT mice." (PMID 23285133, 2012). "Increasing expression of ICOS and CXCR5 on CD4+ T cells has also been reported, and circulating Tfh numbers increase for the duration of infection, thus, the increase in ICOS and CXCR5 may be attributed to the enhanced differentiation of Tfh, and increased glycolysis." (PMID 35493515, 2022). "Thus, the ICOS+PD-1+ cTfh subset presence in recovered individuals could be related to past inflammation during infection." (PMID 35069575, 2021). "Indeed, in the context of murine Plasmodium infection, ICOS appears to play a more substantial role in promoting Ab production late in the infection, suggesting that B cells may be the most important source of ICOSL stimulation for Tfh cell maintenance." (PMID 27559335, 2016). "Importantly, at the infection site, in the absence of Tfh cells, we found that ICOS deficiency actually led to an increased percentage of CD4+ T cells producing IL-4 and IL-13 protein." (PMID 23319295, 2013). "PD-1 and ICOS declined on functional HCV-specific CD4+ T cells with control of viremia, as observed in humans with resolving infections." (PMID 40956619, 2025). "In the liver, CTLA-4 (P = 0.0473), TCR (P = 0.0470), ICOS (P = 0.0382), CD28 (P = 0.0072) and Bcl-2 (P = 0.0462) were upregulated in undernutrition 75% + infection group at the 5th week post-infection." (PMID 38185681, 2024). "During the acute stage of infection, a smaller proportion of CD4+ T cells from TfrcY20H/Y20H mice expressed B cell co-stimulation receptor ICOS." (PMID 37812650, 2023). "Tr1 cells also showed significant activation during infection, with marked upregulation of CD38 and ICOS during infection." (PMID 37968278, 2023).
infection (continued). "Splenic IAV-specific CD4 T cells were also activated by the re-infection, increasing their expression of CD69 and ICOS, although the expression of Ifnγ was equivalent to that in memory animals." (PMID 37842651, 2023). "When Tr1 cells from the same individuals at days 0 and 16 p.i. were compared, the expression of BLIMP-1, CCR5, Tbet, ICOS, cMAF, CTLA4, and PD1, as well as the frequency of Tr1 cells expressing these molecules was significantly increased following infection." (PMID 36594463, 2023). "Future clonality studies involving the LN would give more clarity to this standardization, as well as possibly incorporating markers such as CXCR3, ICOS, CD38 or HLA‐DR to identify acute specific cTfh cells after infection or vaccination." (PMID 36825370, 2023). "The percentages of CD69, ICOS, or CD80-expressing B cells increased in infected mice during the course of infection (p < 0.01)." (PMID 33588839, 2021). "On day 8 after infection with the LCMV Armstrong strain, Ezh2fl/flCd4-Cre mice exhibited a remarkable reduction in the virus-specific GP66–77 tetramer-positive CXCR5+ICOS+ TFH cell population in the spleen compared to that in Ezh2fl/fl control mice." (PMID 30842630, 2020). "On day 5 of infection, Ag-expCD4+ T cells were highly proliferative and exhibited a proinflammatory phenotype, as defined by production of IFN-γ and expression of Ki67, ICOS, and CD25." (PMID 32817333, 2020). "CD28 and ICOS, co-stimulatory receptors important for signaling through the TCR, were both downregulated by infection." (PMID 32452381, 2020). "By day 8 p.i. greater than 90% of the NK1.1+CD4+ T cells expressed ICOS, and the frequency of ICOS+ cells remained significantly higher amongst the NK1.1+CD4+ T cells through the peak of infection." (PMID 30374346, 2018). "Taken together, these studies strongly suggest that ICOS plays a critical role in CD4+ and CD8+ T cell response in both intra and extracellular infection." (PMID 29892278, 2018). "In agreement, at week 2 post-infection a reduced frequency of infiltrating CD4+ T cells expressing deactivation or suppressive molecules (CTLA4, GITR, ICOS) were seen in the lungs of pDC-depleted mice." (PMID 27992577, 2016). "Upon investigation of responsive T cells in this infection, we observed a dramatic increase in CXCR5, ICOS, and SLAM." (PMID 26646149, 2015). "Of note, neonatal mice displayed 3–4 fold more lung ILC2s (lineage- CD45+ ICOS+ ST2+; gating strategy in S1 Fig; raw numbers in S3 Fig) at baseline (i.e. prior to infection) compared to adults." (PMID 26473724, 2015). "The data also showed that the expression of ICOS was significantly down-regulated in ICOSL KO mice compared to WT controls at 4, 7, 12, and 16 weeks post-infection." (PMID 25590646, 2015). "The expression levels of ICOS and ICOSL in splenocytes of the WT mice were elevated at 4 weeks post-infection and peaked at 12 weeks before decreasing gradually." (PMID 25590646, 2015). "Upon infection, the percentage of apoptotic Annexin V+ CD25+ Treg cells increased in both strains, remaining significantly higher in the ICOS−/− mice." (PMID 23319295, 2013). "The transcript abundance of costimulatory molecules (such as CD86, ICOS), CAMs, and TCRs/CD3 complex as well as co-receptor molecules (such as CD8A, CD8B) was remarkably increased after infection with N-PRRSV." (PMID 20614006, 2010). "However, after infection, CD103−CD8+ T cells were activated, with upregulated expression of CD69, ICOS, PD-1, and TIGIT (p < 0.05)." (PMID 41459157, 2025). "IAV-specific CD4 T cells in the lung did not display increased expression of CD69, ICOS, or Ifnγ following re-infection." (PMID 37842651, 2023). "Ki67 but not ICOS expression was higher on both Th1- and Th2-Tfh cells in children with a current asymptomatic infection." (PMID 35851033, 2022).
infection (continued). "Indeed, of the markers examined, 2° effector OT‐I cells and 1° effector OT‐I cells differed only in ICOS expression, which was higher on 1° effector OT‐I cells during primary PbA‐OVA infection." (PMID 34407221, 2021). "Remarkably, a TCM cell subset (Sp cluster 8), characterized by expression of CD27hi, CD127, and CD278 (ICOS) was found in the spleen upon infection with LCMV Armstrong and LCMV clone 13 but not MCMV." (PMID 33458613, 2021). "While we cannot rule out that CQ treatment negatively impacts memory T cell formation, the elimination of an antigen source, in this case, influenced the ability of mice, especially in the absence of ICOS, to generate memory T cell populations after infection." (PMID 32348365, 2020). "During the early acute stage of infection with T. gondii, ICOS KO mice have been reported to have sub-optimal T cell proliferation and IFN-γ production, though these mice were still able to control the parasite and survive to the later stages of infection." (PMID 31978191, 2020). "Nevertheless, the role of ICOS in the formation of memory CD4+ T cells appears to be context-dependent and could be influenced by the length of the infection." (PMID 32348365, 2020). "A lack of expansion in Tfh cells in Icos-/- mice after secondary infection suggests that Ab production is compromised in the absence of ICOS." (PMID 32348365, 2020). "Consistent with this, in our experiment during blood stage PbA infection, ICOS may be involved in the activation of splenic CD4+ and CD8+ T cells as both these cells express significantly higher ICOS." (PMID 29892278, 2018). "Thus, we analyzed co-expression of ICOS and T-bet by CD4+ and CD8+ T cells during blood stage PbA infection." (PMID 29892278, 2018). "Similar to the results seen with infection models that induce a Th1 response, the absence of ICOS signaling did not completely suppress the development of Th2 immunity." (PMID 27559335, 2016). "Irrespective of tissue origin, ICOS was expressed at significantly higher levels on infection-induced CD4+ YFP+ GFP+ T cells than on the corresponding CD4+ YFP+ GFP− T cells." (PMID 26459508, 2016). "Here we show that upon infection, Tregs upregulate CTLA-4, CD103, ICOS, PD-1 and GITR." (PMID 25050936, 2014). "Alongside the expected upregulation of ICOS by CD4+Foxp3− Teff cells during both infections, CD4+Foxp3+ Treg cells showed increased expression of ICOS over the first 4 weeks of H. polygyrus infection and during the acute egg phase (weeks 6–8) of S. mansoni infection." (PMID 23319295, 2013). "Upon H. polygyrus infection the numbers of Foxp3+ Treg cells in the MLN of WT mice significantly increased 73% by day 7 post-infection (pi), however, there was no early expansion of Foxp3+ Treg cells at this time point in ICOS−/− mice." (PMID 23319295, 2013). "Costimulatory molecules (CD80, CD86, CD40, GITR, and ICOS), adhesion molecules (VCAM-1 and P-selectin), and signaling molecules involved in cytokine regulation (Tbx21 and Socs1) were also increased with Hb infection and decreased with anti-IL-7Rα M595 treatment in a dose-dependent manner." (PMID 23057802, 2012). "We also assessed ILC2 responses in MLNs from naive and infected mice, defined as lineage-negative (Lin−) CD45+ICOS+GATA3+ cells; both the percentages and total numbers were greatly reduced in MIF-deficient mice, with no increase apparent following infection." (PMID 35288645, 2022). "Moreover, even if not significant, the frequency of the cTfh1 ICOS+ PD-1+ subset was higher in individuals with early infection than in individuals with a longer time post-infection." (PMID 35069575, 2021). "The inability of memory T cells to adopt a Tfh cell effector phenotype in the absence of ICOS likely compromised their ability to provide help to B cells, particularly MBCs, after re-infection leading to the observed impairment in parasite-specific Ab production." (PMID 32348365, 2020).
infection (continued). "In addition to elevated levels of CD44, Tregs in IFNARflf/fl x Foxp3YFP-Cre mice also expressed higher percentages of other activation markers, including Ki-67+, ICOS+ and TIGIT+, consistent with an activated phenotype and greater degree of proliferation at day 5 post Armstrong infection." (PMID 29672594, 2018). "Although earlier studies have examined the role of ICOS in the control of acute blood-stage infection of Plasmodium chabaudi chabaudi AS (a non-lethal model of malaria infection), its significance in the lethal blood-stage of PbA infection remains unclear." (PMID 29892278, 2018). "ICOS, a co-stimulatory molecule implicated in the induction and maintenance of Tfh cells, was expressed on both NK1.1 positive and negative CD4+ T cells on day 5 after infection." (PMID 30374346, 2018). "Neither IL-27 nor ICOS played a role in the development of parasite-specific CD4+ YFP+ T cell responses during infection, implying that these pathways specifically modify the induction of IL-10 expression, rather than modifying the initial development of the Th1 response." (PMID 26459508, 2016). "When compared with the data presented here, these studies indicate that the importance of ICOS signals in a CD4+ T‐cell response may be dictated by the route of antigen encounter, for example i.v. or i.n. infection with Lm‐2W1S results in very different memory cell responses." (PMID 25754933, 2015). "A recent study in mice reported that memory TFH cells have reduced mRNA expression of TFH markers such as Bcl6, IL-21, ICOS and PD-1 compared to the effector TFH population, indicating the expression of these molecules may change depending on the phase of infection." (PMID 24497824, 2014). "In this light, we measured CD25, CD44, and ICOS as markers of activation, which might correlate with Helios expression, but found this not to be the case either at steady state or following infection." (PMID 24185641, 2014). "Moreover, in Hodgkin’s lymphoma, genetic analysis determined that CXCR5+ ICOS+ CD8+ T cells are most closely related to CD4-derived Tfh than other cell populations, and thus these cells may undergo similar metabolic alterations under conditions of infection." (PMID 35493515, 2022). "However, information regarding whether ICOS expression by memory CD4+ T cells has a direct effect on the ability of these cells to adopt a Tfh phenotype in response to antigen re-challenge is limited, specifically in the context of infection." (PMID 32348365, 2020). "Minimal ICOS expression was found on B cells, NK cells, and NKT cells in PbA infected and uninfected mice (data not shown) that did not vary with progressive infection." (PMID 29892278, 2018). "M.tb-specific FoxP3+ T cells have been currently discussed to enrich in mice peripheral lymphoid nodes after infection with M.tb; those Treg-like cells were activated by expressing high amounts of cell surface CD25, CTLA-4, GITR, CD103, and ICOS, but not producing IFN-γ." (PMID 33977110, 2021). "However, capacity to control the chronic phase of infection, which is controlled by CD8+ T cells, was impaired without ICOS expression indicating a role for ICOS in CD8+ T cell functions." (PMID 30631323, 2018). "CD4+ T cells do not commit to the Tfh lineage until days 6–10 of infection 39, and at day 7 of H. polygyrus infection, on the cusp of Tfh-cell commitment, the numbers of IL-4 and IL-13 producing CD4+ T cells in the MLNs were equivalent in WT and ICOS−/− mice." (PMID 23319295, 2013). "In the context of Mycobacterium tuberculosis infection, for example, mice lacking expression of ICOS exhibited evidence of enhanced Th1 immunity, producing a significantly greater number of CD4+IFN-γ+ T cells in the spleen and lungs during later stages of infection." (PMID 27559335, 2016).
inflammation (9 papers, 2007 to 2025). Aberrant reaction of the microcirculation characterized by movement of fluid and leukocytes from the blood into extravascular tissues. "Together, our results suggest that ICOS deficiency promotes IL-10 production in ILC2s and that IL-10 plays a role in regulation of ILC2-induced AHR and lung inflammation in ICOS-KO mice." (PMID 40627441, 2025). "The loss of ICOS on murine ILC2s or blocking of the ICOS:ICOSL interactions in human ILC2s reduced airway hyperreactivity and lung inflammation by interfering with cytokine-dependent STAT5 activation and resulting impairment in IL-13 release." (PMID 31574995, 2019). "In this study, to identify the detailed role of IL-25 in promoting innate immune responses in asthmatic airway inflammation, the expression levels of ICOS and T1/ST2 on nuocytes were detected by means of flow cytometry." (PMID 27617447, 2016). "Using ICOS+/+ and ICOS+/− mice in a Th2 model of airway inflammation, we found that T cells from the ICOS+/− mice had reduced ICOS expression and decreased Th2-mediated inflammation in vivo." (PMID 19888475, 2009). "This scenario is supported by observations that ICOS blockade in vivo is particularly effective when given during the late (effector) phase of Th1/Th17-mediated EAE or Th2-mediated airway inflammation." (PMID 17549732, 2007). "In addition to these ICOS-knockout studies, we and others have shown that blocking ICOS inhibits Th2-mediated lung inflammation, and ICOS blockade in vitro resulted in a corresponding decrease in IL-4 and IL-5 production by Th2 cells." (PMID 19888475, 2009). "To explore how the level of ICOS-B7RP-1 interactions can regulate Th2 responses, we used a model in which ICOS cell-surface expression levels are pre-determined and compared the responses of ICOS+/+ mice and ICOS+/− mice in an established airway inflammation model." (PMID 19888475, 2009). "To test our hypothesis we analyzed the Th2 in vivo response of ICOS+/+, ICOS+/−, and ICOS−/− mice using an established Th2-mediated airway inflammation model." (PMID 19888475, 2009). "In contrast, CD25low ILC2s, exhibiting lower surface expression of T1/ST2, ICOS, and KLRG1 and a more modest cytokine production capacity, dominated in our chronic HDM airway inflammation model." (PMID 29250067, 2017).
bacterial infections (3 papers, 2015 to 2025). "In summary, beyond the formation of Tfh cells, signals through ICOS appear critical for the generation of a functional pool of Tem and Tcm cells following acute bacterial infection." (PMID 25754933, 2015).
Connective Tissue Diseases (2 papers, 2022). "Altogether, the preclinical and clinical results support a role for both the ICOS and CD28 pathways in connective tissue disorders, and our data herein extend the findings to the specific fibrotic phenotype that characterizes SSc." (PMID 34986869, 2022).
hematologic malignancies (2 papers, 2023 to 2024). "Considering these results, immunotherapeutic targeting of TFH cells, for instance, through anti-ICOS mAbs, currently tested in other hematologic malignancies, is a promising perspective." (PMID 39273028, 2024).
infectious disease (2 papers, 2015 to 2018). A disorder directly resulting from the presence and activity of a microbial, viral, or parasitic agent in humans. "The role of the ICOS/ICOSL pathway in T. cruzi infection is not well understood, but ICOS plays a crucial role in T cell responses in other infectious diseases caused by protozoans." (PMID 30405039, 2018). "The ICOSL/ICOS pathway plays different roles in different models of autoimmune and infectious disease." (PMID 25590646, 2015).
adenocarcinoma (1 paper, 2023). A common cancer characterized by the presence of malignant glandular cells. "Also using immunohistochemical analysis, a previous study evaluated the expression level of immune checkpoint markers in adenocarcinoma (n = 142), which involves ICOS." (PMID 37850501, 2023).
neuromuscular disease (1 paper, 2017). "High grade immune infiltration was detected in muscles and peripheral nerves of 40-week-old female ICOS+/+ICOSL−/− NOD mice but also in male ICOS+/+ICOSL−/− NOD mice despite the lower prevalence of clinical neuromuscular disease (data not shown)." (PMID 28424681, 2017).